COL6A1 (collagen type VI alpha 1 chain)
Description:
Collagen VI acts as a cell-binding protein.
Synonyms: BTHLM1; BTHLM1A; OPLL; UCHMD1; UCHMD1A
Tractability: Antibody: its Gene Ontology location is reachable by antibodies, with high confidence; UniProt places it where antibodies can reach, with medium confidence; UniProt predicts a signal peptide or a membrane-spanning region. PROTAC: ubiquitination databases record sites on it; its protein half-life has been measured. Other modalities: an approved drug acts on it.
Gene: Protein-coding gene on chromosome 21 (45,981,755 to 46,005,050, forward strand). Ensembl gene ENSG00000142156.
Subcellular location: Secreted, extracellular space, extracellular matrix
Subcellular location (Human Protein Atlas): Cytosol; Predicted to be secreted
Pathways (Reactome):
Extracellular matrix organization: Assembly of collagen fibrils and other multimeric structures; Collagen biosynthesis and modifying enzymes; Collagen chain trimerization; Collagen degradation; ECM proteoglycans; Integrin cell surface interactions
Developmental Biology: NCAM1 interactions
Signal Transduction: Signaling by PDGF
Gene Ontology:
Molecular function: collagen binding; platelet-derived growth factor binding; protein binding; extracellular matrix structural constituent conferring tensile strength
Biological process: endodermal cell differentiation; osteoblast differentiation; skeletal muscle fiber development; anatomical structure morphogenesis; cell differentiation; tissue development
Cellular component: extracellular exosome; extracellular matrix; extracellular region; lysosomal membrane; membrane; protein-containing complex; collagen type VI trimer; endoplasmic reticulum lumen; microfibril; basement membrane; endoplasmic reticulum; intracellular vesicle; lysosome; myofibril; sarcolemma; sarcoplasmic reticulum
Genetic constraint (gnomAD): Loss-of-function variants: 80 observed, 136.52 expected, observed/expected ratio (o/e) 0.59, 90% interval 0.49 to 0.71. The upper end of that interval is the gene's LOEUF score, 0.71, which puts it in group 2 of 6, group 1 being the genes least tolerant of losing a copy. Missense variants: 1,364 observed, 1,404.8 expected, observed/expected ratio (o/e) 0.97, 90% interval 0.93 to 1.01. Synonymous variants: 638 observed, 604.88 expected, observed/expected ratio (o/e) 1.05, 90% interval 0.99 to 1.13.
Gene-disease validity (ClinGen):
ClinGen rates the evidence that COL6A1 causes each of these diseases.
collagen 6-related myopathy (autosomal dominant; autosomal recessive): Definitive. A qualitative or quantitative defect of collagen 6 disorder that covers a wide spectrum of musculoskeletal phenotypes caused by dominant and recessive mutations in the three major collagen VI genes: COL6A1, COL6A2, and COL6A3.
Homologues: Orthologues: macaque COL6A1 (98% identical), dog COL6A1 (91% identical), pig COL6A1 (91% identical), mouse Col6a1 (90% identical), rat Col6a1 (89% identical), zebrafish col6a1 (54% identical). Paralogues in human: COL6A2 (35% identical), COL5A1 (26% identical), COL11A1 (25% identical), COL11A2 (24% identical), COL1A1 (23% identical), COL5A2 (23% identical), COL2A1 (23% identical), COL4A5 (22% identical), COL3A1 (22% identical), COL4A1 (22% identical), COL5A3 (22% identical), COL4A6 (22% identical), and 25 more.
Diseases named in the same sentence as COL6A1 in open-access papers:
COL6A1 is named in the same sentence as 163 diseases in open-access papers, as found by Europe PMC text mining. Sharing a sentence is not in itself a finding about the gene and the disease. The quoted sentences say what the papers report.
Ullrich congenital muscular dystrophy (46 papers, 2010 to 2026). Ullrich congenital muscular dystrophy (UCMD) is characterized by early-onset, generalized and slowly progressive muscle weakness, multiple proximal joint contractures, marked hypermobility of the distal joints and normal intelligence. "Mutations in the type VI collagen gene are associated with muscular weakness disorders; for instance, mutations in COL6A1 can lead to Bethlem myopathy and Ullrich congenital muscular dystrophy." (PMID 40563444, 2025). "In the CM group, we identified the COL12A1 variant c.5894G>A and the COL6A1 variant c.850G>A, which have been previously reported in patients with Bethlem myopathy or Ullrich congenital muscular dystrophy." (PMID 38818036, 2024). "A novel homozygous splice site variant in COL6A1 causing Ullrich congenital muscular dystrophy in a Malian family, emphasizing the importance of genetic studies in African cohorts to advance epidemiological knowledge and therapeutic development." (PMID 39523858, 2024). "By contrast, Stickler syndrome has the most collagens (six) linked to this syndrome (COL2A1, COL9A1, COL9A2, COL9A3, COL11A1, and COL11A2), followed by Ullrich congenital muscular dystrophy, with four collagens associated (COL6A1, COL6A2, COL6A3, and COL12A1)." (PMID 37189830, 2023). "Ullrich congenital muscular dystrophy (UCMD) is a rare disease caused by mutations in the COL6A1, COL6A2 or COL6A3 genes leading to deficiency of collagen VI in extracellular matrices (ECM)." (PMID 35925158, 2022). "Mutations in COL6A1 have been reported to cause, among others, Bethlem myopathy (omim.org/entry/158810) and Ullrich Congenital Muscular Dystrophy 1 (omim.org/entry/254090) characterized by increased skeletal muscle weakness and joint stiffness in infancy." (PMID 31254144, 2019). "Ullrich congenital muscular dystrophy (UCMD) is caused by mutations in collagen VI genes (COL6A1, COL6A2 and COL6A3) and is characterised by congenital hypotonia, proximal muscle weakness and distal joint hyperlaxity." (PMID 26670220, 2015). "Mutations of COL6A1 encoding collagen type VI has been linked to Ullrich congenital muscular dystrophy (UCMD) characterized by early-onset and generalized muscle weakness, and Bethlem myopathy (BM) characterized by proximal muscle weakness and flexion contractures." (PMID 36312227, 2022). "Other congenital muscular dystrophies such as merosin-deficient congenital muscular dystrophy type 1A (LAMA2 deficiency) or Ullrich congenital muscular dystrophy (mutations in COL6A1, 2 or 3) are also characterized by muscle degeneration and fibrosis accumulation." (PMID 34875199, 2021). "Several mutations of COL6A1, 2, and 3 genes cause Ullrich congenital muscular dystrophy (UCMD)." (PMID 34372931, 2021). "Disorders caused by mutations of COL6A1 genes mainly affect ligaments and muscles; mutations of the COL6A1 polypeptide chains are causative of a broad spectrum of diseases in humans, including Ullrich congenital muscular dystrophy and C-OPLL." (PMID 31831033, 2019). "Variants in the human COL6A1 gene cause Bethlem myopathy or Ullrich congenital muscular dystrophy." (PMID 26438297, 2015). "Ullrich congenital muscular dystrophy (UCMD), Bethlem myopathy (BM), and myosclerosis myopathy (MM) are diseases caused by mutations in each of the three genes (COL6A1, COL6A2, and COL6A3) encoding the extracellular matrix protein collagen VI." (PMID 32053901, 2020). "COL6A1/COL6A2/COL6A3 mutations cause severe Ullrich congenital muscular dystrophy (UCMD) and milder Bethlem myopathy, which can be inherited as autosomal dominant or recessive disorders, but collagen VI mutations can also affect the skin and tendon." (PMID 31387942, 2019). "COL6A1 is actually a very good functional candidate gene for a muscular dystrophy as genetic variants in this gene cause different human myopathies with variable clinical phenotypes ranging from the milder Bethlem myopathy to the severe Ullrich congenital muscular dystrophy." (PMID 26438297, 2015).
Ullrich congenital muscular dystrophy (continued). "Pathogenic or likely pathogenic variants were detected in 31 distinct genes, including COL6A1 and COL6A3, which are associated with Ullrich congenital muscular dystrophy." (PMID 41828661, 2026). "This group includes collagen VI‐related dystrophies such as Ullrich congenital muscular dystrophy (UCMD) and Bethlem myopathy (BM), caused by mutations in the COL6A1, COL6A2 and COL6A3 genes." (PMID 39523858, 2024). "Mutations in COL6A1, COL6A2, and COL6A3 lead to a spectrum of collagen VI-related muscular dystrophies, ranging from the severe Ullrich congenital muscular dystrophy (UCMD) via intermediate phenotypes to the milder Bethlem muscular dystrophy (BM)." (PMID 40225172, 2023). "Mutations in COL6A1, COL6A2, and COL6A3 lead to the severe Ullrich Congenital Muscular Dystrophy (UCMD) and a spectrum of disease of varying severity including the milder Bethlem muscular dystrophy." (PMID 40225172, 2023). "Mutations in the genes encoding COL6A1 and COL6A2 have been associated with certain diseases, including Bethlem Myopathy and Ullrich Congenital Muscular Dystrophy." (PMID 37842511, 2023). "This was, for instance, the case for COL6A1, associated with Bethlem myopathy 1 (OMIM #158810) and Ullrich congenital muscular dystrophy 1 (OMIM #254090), and for IQSEC1, associated with severe ID (OMIM #618687)." (PMID 38137073, 2023). "Dominant-negative mutations in the genes that encode the three major α chains of collagen type VI, COL6A1, COL6A2, and COL6A3, account for more than 50% of Ullrich congenital muscular dystrophy patients and nearly all Bethlem myopathy patients." (PMID 28918041, 2017). "Mutations in genes encoding collagen VI (i.e., COL6A1, COL6A2, and COL6A3) have been identified as causative in Ullrich congenital muscular dystrophy (UCMD) and Bethlem myopathy (BM)." (PMID 26753503, 2016). "Deficiency of ColVI due to mutations in COL6A1, COL6A2, or COL6A3 gives rise to three main muscle disorders, Ullrich congenital muscular dystrophy (UCMD, MIM #254090), Bethlem myopathy (BM, MIM #158810), and myosclerosis myopathy (MIM #255600)." (PMID 25477819, 2014). "Likewise, COL6A1 myopathies are characterized by an excessive accumulation of PDGFRα+ cells and fibrosis in mouse model and in patients affected by Ullrich congenital muscular dystrophy." (PMID 34875199, 2021). "Thus, the Landseer dogs with the COL6A1:c.289G>T variant are potentially an interesting animal model for human Ullrich congenital muscular dystrophy as they resemble the severe human clinical phenotype much closer than Col6a1−/− knock out mice." (PMID 26438297, 2015). "In humans, mutations in any of the three genes coding for collagen VI (COL6A1, COL6A2, COL6A3) result in defective ECM composition and cause a wide clinical spectrum of collagen VI myopathies including Ullrich congenital muscular dystrophy (UCMD), Bethlem myopathy (BM) and myosclerosis myopathy." (PMID 23437220, 2013). "COL6A1 silencing in Ullrich congenital muscular dystrophy (UCMD) showed low editing efficiencies (<1%), underscoring the challenges of HDR-dependent correction." (PMID 41188549, 2025). "Mutations in the COL6A1, COL6A2, and COL6A3 genes result in either the absence or malformation of the microfibrils, causing a spectrum of muscle disorders: Bethlem myopathy (BM, MIM 158810), Ullrich congenital muscular dystrophy (UCMD, MIM 254090), and myosclerosis myopathy (MM, MIM 255600)." (PMID 37569848, 2023). "Mutations in the COL6A1, COL6A2, and COL6A3 genes cause collagen VI-related myopathies (COL6-RM) that include Ullrich congenital muscular dystrophy (UCMD), Bethlem myopathy (BM), and myosclerosis myopathy (MM)." (PMID 37047652, 2023). "Deficiency of collagen type VI (Col VI) caused by mutations of COL6 genes (COL6A1, COL6A2, and COL6A3) gives rise to three main muscle disorders: Bethlem myopathy (BM), Ullrich congenital muscular dystrophy (UCMD), and myosclerosis myopathy." (PMID 33086603, 2020).
Ullrich congenital muscular dystrophy (continued). "Spermidine was found to ameliorate myopathic defects in the animal model of Ullrich congenital muscular dystrophy (UCMD) and Bethlem myopathy (BM) (col6a1−/− mice) by reactivating autophagy in skeletal muscle." (PMID 29443878, 2018). "Mutations in COL6A1, COL6A2 and COL6A3 encoding collagen VI, cause Ullrich congenital muscular dystrophy (UCMD), Bethlem myopathy (BM) and myosclerosis myopathy." (PMID 25158062, 2014). "Mutations in COL6A1, COL6A2 and COL6A3 genes result in collagen VI myopathies: Ullrich congenital muscular dystrophy (UCMD), Bethlem myopathy (BM) and intermediate phenotypes." (PMID 22075033, 2012). "Mutations in the genes encoding collagen VI (COL6A1, COL6A2 and COL6A3) result in two major phenotypes: Bethlem myopathy [BM, OMIM #158810] and Ullrich congenital muscular dystrophy [UCMD, OMIM #254090]." (PMID 20302629, 2010). "Mutations in any of the three collagen 6A genes COL6A1, COL6A2 and COL6A3 result in Ullrich congenital muscular dystrophy (UCMD), Bethlem myopathy (BM) or phenotypes intermediate between UCMD and BM, characterised by a combination of distal laxity, proximal muscle weakness and joint contractures." (PMID 22075033, 2012). "Mutations of COL6 genes (COL6A1, COL6A2, and COL6A3) cause COL6-related myopathies, a group of rare inherited muscle diseases that include Bethlem myopathy (BM) and Ullrich congenital muscular dystrophy (UCMD), as well as the limb girdle and myosclerosis myopathy variants." (PMID 27656840, 2016).
Bethlem myopathy (28 papers, 2011 to 2025). A usually autosomal dominant inherited movement disorder caused by mutations in the COL6A1, COL6A2, and COL6A3 genes. "Whole exome sequencing (WES) subsequently identified a heterozygous pathogenic splice-site variant (c.1056+1G>A) in the COL6A1 gene, confirming a diagnosis of Bethlem myopathy type 1, an autosomal dominant collagen VI-related disorder." (PMID 41439068, 2025). "Col6a1 expression was particularly notable because its mutation causes Bethlem myopathy, which is characterized by deficits at the MTJ32." (PMID 33311457, 2020). "Bethlem myopathy is almost exclusively caused by dominant COL6A1, COL6A2, or COL6A3 mutations, whereas UCMD occurs as a result of both recessive and dominant mutations." (PMID 28918041, 2017). "SNV analysis also revealed a missense Variant of Uncertain Significance (VUS) in 1 UMD and 1 suspected LGMD case in COL6A2 (P52) and COL6A1 (P97) gene, respectively which causes Bethlem myopathy 1 (LGMD R22 Collagen6-related) disease as per the Clinvar database." (PMID 34925456, 2021). "COL6A1 mutations have been linked to Bethlem myopathy with joint contractures." (PMID 27146865, 2016). "Analysis of Col6a1−/−mice that develop Bethlem myopathy provided key insights into the disease mechanisms, including a role for neuromuscular junction and muscle stem cell defects." (PMID 31387942, 2019). "Dominant negative mutations in the COL6A1 gene, the only collagen that was investigated in the current study, are known to lead to Bethlem myopathy and Ulrich congenital muscle dystrophy; COL6A1 knockout mice exhibit sarcolemmal disorganization." (PMID 21385442, 2011). "Even though phenotypic overlap between patients with COL12A1‐related myopathy and patients with Bethlem myopathy, a form of COL6‐related dystrophy due to mutations in collagen VI genes (COL6A1, COL6A2, or COL6A3) has been noted, several features help distinguish these disorders." (PMID 31509352, 2019). "Some heterozygous premature termination codon (PTC) mutations in COL6A1 cause Bethlem myopathy but they are non-pathogenic when they occur in COL6A2/COL6A3." (PMID 31387942, 2019). "The Col6a1−/− mouse model is widely studied, as it resembles human Bethlem myopathy and UCMD." (PMID 23437220, 2013).
osteosarcoma (21 papers, 2021 to 2025). A usually aggressive malignant bone-forming mesenchymal neoplasm, predominantly affecting adolescents and young adults. "In line with the heterogeneity of osteosarcoma, we found subpopulations of osteosarcoma cells that highly expressed COL6A1, COL6A3 and MIF and were closely associated with lung metastasis." (PMID 35463309, 2022). "COL6A1 is packaged into osteosarcoma cell-derived exosomes and activates cancer-associated fibroblasts in TME." (PMID 36167487, 2022). "In osteosarcoma and lung metastasis, COL6A1 is associated with a worse prognosis." (PMID 38031074, 2023). "These activated CAFs enhance the invasion and migration of osteosarcoma cells through the TGF-β/COL6A1 signaling pathway." (PMID 40940809, 2025). "Exosomal collagen type VI alpha 1 (COL6A1) contained in osteosarcoma (OS) cells induces the transfer of normal fibroblasts into CAFs by secreting IL-6 and IL-8." (PMID 38495881, 2024). "Exosomal collagen type VI alpha 1 (COL6A1), transforms healthy fibroblasts into CAFs, facilitating the invasion and migration of osteosarcoma (OS) cells via the TGF-β/COL6A1 signaling pathway." (PMID 39187523, 2024). "The signaling role of COL6A1 is very important in tumors as it increases tumor cell proliferation in osteosarcoma as well as promotes vascular invasion and distant metastasis in pancreatic carcinoma." (PMID 37218885, 2023). "H3K27 acetylation activated‐COL6A1 promotes osteosarcoma lung metastasis by repressing STAT1 and activating pulmonary cancer‐associated fibroblasts." (PMID 37143582, 2023). "STAT1 significantly increases cell cycle arrest and apoptosis and decreases the capability of colony formation, cell migration, and cell invasion by suppressing epithelial-mesenchymal transition in osteosarcoma cells with COL6A1 overexpression." (PMID 37514090, 2023). "Additionally, COL6A1 is packaged into osteosarcoma-derived exosomes, which convert normal fibroblasts into cancer-associated fibroblasts (CAFs) that secrete IL-6 and Interleukin-8 (IL-8)." (PMID 40940809, 2025). "Additionally, genes like COL6A1, COL6A3, and MIF were associated with lung metastasis, indicating that a highly invasive subcluster in osteosarcoma correlated with a poor prognosis." (PMID 39324133, 2024). "Interestingly, AKT phosphorylation was shown to be similarly affected upon COL6A3 siRNA-mediated silencing in osteosarcoma cells, also displaying a marked deregulation upon COL6A1 and COL6A2 modulation in bladder cancer cells." (PMID 37505240, 2023). "In osteosarcoma tissues, collagen type VI alpha 1 (COL6A1) is highly expressed." (PMID 37514090, 2023). "Notably, some studies have revealed that the transcription factor c-Jun-bound p300 increases the enrichment of H3K27ac at the promoter region of COL6A1, thus resulting in the upregulation of COL6A1 in osteosarcoma (OS)." (PMID 34966737, 2021). "However, the role of COL6A1 in osteosarcoma (OS) progression remains largely unclear." (PMID 33391546, 2021). "COL6A1 is dysregulated in several human malignancies, and upregulation of H3K27 acetylation-activated COL6A1 promotes cell migration and invasion by inhibiting the STAT1 pathway in OS cells and promotes osteosarcoma lung metastasis." (PMID 36171897, 2022). "PODN was regarded as a potential biomarker for the diagnosis and prognosis of osteosarcoma, ACTA2, COL6A1, FAP, OLFML2B and COL6A3, can be used as potential prognostic indicators for osteosarcoma." (PMID 34273970, 2021). "Furthermore, ACTA2, COL6A1, FAP, OLFML2B and COL6A3, can be used as prognosis biomarkers for osteosarcoma." (PMID 34273970, 2021). "Finally, it was determined that PODN has functional relevance in osteosarcoma and additional genes (ACTA2, COL6A1, FAP, OLFML2B and COL6A3) have prognostic significance for osteosarcoma." (PMID 34273970, 2021).